SP4 (Sp4 transcription factor)
Diseases named in the same sentence as SP4 in open-access papers (continued):
Sharing a sentence is not in itself a finding about the gene and the disease.
cancer (continued). "Deregulated activity of transcription factors (TFs) of the Sp/KLF family, like Sp1, Sp3 and Sp4, and consequent over-expression of Sp-regulated genes occur frequently in human cancers." (PMID 22545098, 2012). "Previous studies by RNA interference (RNAi) show that both survivin and bcl-2 are regulated by Sp1, Sp3 and Sp4 in cancer cells." (PMID 23110215, 2012). "Sp1, Sp3 and Sp4 are overexpressed in multiple cancer cell lines and tumor types and Sp-regulated genes and oncogenes play an important role in cancer cell proliferation, survival, angiogenesis and inflammation." (PMID 23194063, 2012). "Moreover, since Sp1, Sp3 and Sp4 regulate multiple genes required for cancer cell proliferation, survival and invasion, it has been suggested the Sp TFs are non-oncogene addiction genes." (PMID 39858066, 2025). "Genomic studies on these transcription factors and genes/pathways regulated by Sp1, Sp3 and Sp4 demonstrate their role in the growth, survival and migration/invasion of cancer cells and tumors, and this is consistent with their designation as non-oncogene addiction genes." (PMID 36982239, 2023). "Interestingly, quantities of Sp1, Sp3 and Sp4 were found to be suppressed in ZBTB4-overexpressing cancer cells." (PMID 36615262, 2022). "Moreover, betulinic acid exerted repressive effects on the levels of Sp1, Sp3 and Sp4 in tumor tissues of mice xenografted with BT474 cancer cells." (PMID 36615262, 2022). "Our results clearly demonstrate for the first time that not only Sp1 but also Sp3 and Sp4 play a role in cancer cell growth, survival and migration/invasion of multiple cancer cell lines and regulate expression of gene products consistent with these observations." (PMID 26967243, 2016). "The functional importance of Sp1, Sp3 and Sp4 in cancer cells has been confirmed by RNA interference (RNAi) showing that knockdown of Sp transcription factors Sp1, Sp3 and Sp4 (singly or combined) decreases cell proliferation, survival, angiogenesis and inflammation." (PMID 26673922, 2015). "Studies in this laboratory have demonstrated that basal expression of genes, such as survivin, VEGF and EGFR, in various cancer cell lines is dependent on specificity protein (Sp) transcription factors Sp1, Sp3 and Sp4 which are highly expressed in many cancer cells and tumors." (PMID 26673922, 2015). "Estrogen receptor: The hormonal regulation of ER-responsive genes has been investigated in breast and other cancer cell lines, and induction or repression of many of these genes by ER ligands primarily involve ER interactions with DNA-bound Sp1 and, in a few cases, Sp3 or Sp4." (PMID 39858066, 2025). "Moreover, several anticancer agents including NSAIDs and GT-094 (a NO-NSAID), curcumin, betulinic acid and synthetic triterpenoids, and arsenic trioxide decrease expression of Sp1, Sp3, Sp4 and Sp-regulated genes in cancer cells and these effects contribute to their anticancer activity." (PMID 23110215, 2012). "Our results showed that miR-27a suppressed ZBTB10 in cancer cells and antisense miR-27a induced ZBTB10 expression with downregulation of Sp1, Sp3, Sp4 and pro-oncogenic Sp-regulated genes." (PMID 34072678, 2021). "Based on our findings, Sp4-regulated ANGPTL4 production promotes the malignancy of GBM, including the acquirement of drug resistance, by inducing cancer stem cell enrichment." (PMID 31717924, 2019). "Further, it has been reported that knockdown or downregulation of Sp1, Sp3, and Sp4 represses expression of Sp-regulated genes, including VEGF and BCL-2, inhibits cancer cell growth, and induces apoptosis." (PMID 23626851, 2013). "UK anti-Sp4 positive individuals identified do not have cancer; however, the UK anti-Sp4 positive sample size is very small and therefore no influence on cancer was examined." (PMID 39514366, 2024).
cancer (continued). "None of the anti-TIF1γ autoantibody positive DM patients who were also positive for anti-Sp4 autoantibodies developed malignancy, as compared with 14% of the anti-Sp4 negative anti-TIF1γ autoantibody positive DM patients who developed CAM." (PMID 39514366, 2024). "Our previous studies also reported similar non-apoptotic cell death in other cancer cell lines after Tat-SP4 treatment." (PMID 36765914, 2023). "In contrast to ANGPTL4, which was extensively studied in various types of cancers, Sp4 expression in tumor specimens has never been evaluated." (PMID 31717924, 2019). "Although there are a few reports indicating that Sp1, Sp3 and Sp4 differentially regulate some genes and coregulate others, the functional roles of Sp3 and Sp4 compared to Sp1 in cancer cells have not been extensively investigated." (PMID 26967243, 2016). "It has also been reported that zinc depletion induces apoptosis and decreases Sp1, Sp3 and Sp4 in cancer cell lines, and we confirmed that aspirin-induced PARP cleavage and downregulation of Sp1, Sp3 and Sp4 was inhibited in RKO and SW480 cells cotreated with aspirin plus ZnSO4." (PMID 23110215, 2012). "Other studies in cancer cell lines showed that several NR4A1-regulated integrins, including β1-, β4-, α5- and α6-integrins, were coregulated by NR4A1 interactions with Sp1, Sp3 and Sp4; however, the role of individual Sp TFs was gene and cell context-dependent." (PMID 39858066, 2025). "Neither of the two adults with anti-Sp4 autoantibodies had CAM; however, we could not detect a significant association between anti-Sp4 and cancer frequency due to the very low frequency of anti-Sp4 autoantibody positive patients." (PMID 39514366, 2024). "Functional studies have demonstrated that the SP-like family of TFs regulates various genes responsible for cancer-related cellular mechanisms; SP1, SP3, and SP4 are also non-oncogene addiction (NOA) genes and thus are important drug targets." (PMID 37998757, 2023). "In summary, this study indicates that Sp1, Sp3 and Sp4 are NOA genes that are highly expressed in tumor vs. non-tumor tissue and regulate expression of pro-oncogenic factors that contribute to cancer cell growth, survival and migration/invasion." (PMID 26967243, 2016).
tumor (31 papers, 1976 to 2025). "In a parallel experiment, combined knockdown of Sp1, Sp3 and Sp4 or individual knockdown of Sp1 in L3.6pL cells used in an athymic nude mouse xenograft model showed that loss of Sp TFs resulted in a significant inhibition of tumor growth and tumor weights." (PMID 26967243, 2016). "Tat-SP4 administration began when the tumor volume reached 60 mm3, with a dosage of 40 mg/kg/day via intraperitoneal (i.p.)injection." (PMID 41471037, 2025). "MDA-MB-231 cells were implanted subcutaneously on 6-week female nude mice and daily intraperitoneal injection (i.p.)of Tat-SP4 at 40 mg/kg started once tumor volume reached 100 mm3." (PMID 37598181, 2023). "Compared to the control group with daily injection of PBS, Tat-SP4 treatment reduced tumor volume by ~60% after 35 days." (PMID 37598181, 2023). "Compared to the control group with a daily injection of PBS, Tat-SP4 reduced tumor volume by ~50% after 46 days of treatment." (PMID 36765914, 2023). "The mice were randomly grouped into the control group and Tat-SP4 treatment group (n = 7) once the tumor volume reached 100 mm3." (PMID 37598181, 2023). "BxPC-3 cells were implanted subcutaneously on 6-week female nude mice, and daily intraperitoneal injection (i.p.)of Tat-SP4 at 40 mg/kg started once tumor volume reached 100 mm3." (PMID 36765914, 2023). "SRSP increased the binding of SRSF3 to exon 3 of transcription factor Sp4, which promoted the formation of “ oncogene” long Sp4 subtype (L-Sp4 protein) and inhibited the formation of “tumor suppressor” short Sp4 isoform (S-Sp4 peptide)." (PMID 34888249, 2021). "SRSP promoted SRSF3 binding to transcription factor Sp4 exon 3, contributed to promoting the formation of the “oncogene” long Sp4 isoform, and restrained the formation of the “tumor suppressor” short Sp4 isoform." (PMID 33088214, 2020). "These functional and quantitative genomic data coupled with the high expression of Sp transcription factors in tumor vs. non-tumor tissue suggests that Sp1, Sp3 and Sp4 are NOA genes and attractive drug targets." (PMID 26967243, 2016). "Lastly, Tat-SP4 inhibited tumor growth in a xenograft-based animal model for SCLC." (PMID 41471037, 2025). "Tat-SP4 significantly inhibited tumor growth compared to PBS." (PMID 41471037, 2025). "There is also extensive evidence that multiple compounds, including approved drugs that are used for other diseases, induce downregulation or degradation of Sp1, Sp3 and Sp4, which is accompanied by inhibition of cell/tumor growth and invasion and induction of apoptosis." (PMID 36982239, 2023). "Tat-SP4 also effectively inhibited tumor growth in a xenograft model of TNBC." (PMID 37598181, 2023). "Except for few being chromatin regulators (CGBP, MBD2, and DNMT1), all of these TFs were found to have tumor suppressor functionality (BRCA1, E2F1&2&5&7, EGR1-4, FLI1, NRF1, TFDP2, and STAT1), or indirectly mediate the suppression of tumorigenesis and tumor suppressor activity (SP4 and ZBTB33)." (PMID 29740534, 2018). "Tumor lysates from control and treated animals were analyzed by western blot analysis for Sp1, Sp3 and Sp4, and levels were quantitated relative to β-actin and showed significant decreases in expression of Sp1, Sp3 and Sp4 in aspirin vs. control animals." (PMID 23110215, 2012). "This demonstrates that, for BA and possibly other drugs that downregulate Sp1, Sp3, Sp4 and Sp-regulated genes, the pathways required for this response are variable and dependent not only on tumor type but also cell context within the same tumor." (PMID 21864401, 2011). "Thus, Tat-SP4 potently inhibited tumor growth in an xenograft model of TNBC in vivo." (PMID 37598181, 2023). "Finally, Sp4 pre‐mRNA splicing was investigated in clinical tumor tissue samples." (PMID 32440474, 2020). "Our results reveal that Tat-SP4 utilized macropinocytosis for cell entry and triggered autosis, a form of autophagy-dependent cell death, in SCLC cells to inhibit tumor growth." (PMID 41471037, 2025).
tumor (continued). "Tat-SP4 exerted a potent anti-proliferative effect in PDAC cell lines in vitro and prohibited xenograft tumor growth in vivo." (PMID 36765914, 2023). "Tat-SP4 exerted a potent anti-proliferative effect in PDAC cell lines in vitro and prohibited tumor growth in the PDAC xenograft model in vivo." (PMID 36765914, 2023). "Betulinic acid downregulated Sp1, Sp3, Sp4 and EZH2 in tumor tissues and this was accompanied by simultaneous decrease in the levels of miR20a, miR-106a and miR-106b." (PMID 36615262, 2022). "SP1, SP4, SP7, and SP8, linked to suboptimal or partial chemotherapy responses, exhibited a predominant tumor cell presence (data not displayed)." (PMID 38975339, 2024). "We also found that the binding proficiency of the Sp transcription factor family (including SP1, SP2, SP4, and SP5) (Rows 17–20) could bind GC/GT-rich promoter elements by its zinc finger structure and play a critical role in tumor growth and metastasis." (PMID 37833332, 2023). "Whether Tat-SP4 affects the levels of LC3 and p62 in these xenograft tumor tissue shall be explored in future studies." (PMID 36765914, 2023). "The total Sp4 mRNA levels between tumor tissues and their matched adjacent nontumoral tissues were not different." (PMID 32440474, 2020). "In a xenograft model of PDAC, Tat-SP4 effectively inhibited tumor growth with no overt toxicity." (PMID 36765914, 2023). "Thus, the oncogenic-like activity of Sp1, Sp3 and Sp4 and Sp-regulated genes coupled with their overexpression in tumor vs. non-tumor tissue suggests that Sp1, Sp3 and Sp4 are non-oncogene addiction (NOA) genes that are “attractive drug targets”." (PMID 26967243, 2016).
psychiatric disorder (7 papers, 2009 to 2024). A disorder characterized by behavioral and/or psychological abnormalities, often accompanied by physical symptoms. "The findings prompted us to examine whether human SP4 gene may associate with psychiatric disorders." (PMID 19401786, 2009). "SP4 is highly expressed in neurons and brain and reduction of SP4 leads to defects in developmental dendrite patterning, hippocampal long-term potentiation, and animal behaviors associated with psychiatric disorders, including deficits in contextual and spatial memory and prepulse inhibition." (PMID 25915526, 2015). "These miRNAs and mRNAs were previously implicated in psychiatric disorders (miR-320a and SP4), key processes of the central nervous system (CAPNS1, RGS16, SP4) or pathways involved in mental illnesses (miR-155-3p)." (PMID 31801218, 2019). "Identifying these pathways is a future goal for better understanding the signaling pathways regulating SP4 and their possible contribution to the pathophysiology and therapy of psychiatric disorders." (PMID 25915526, 2015). "Our data adds further evidence for a role for SP4 phosphorylation at S770 in the post-translational regulation of SP4 in the context of psychiatric disorders." (PMID 25915526, 2015). "Reduced expression of the mouse Sp4 gene results in a variety of behavioral abnormalities relevant to human psychiatric disorders." (PMID 19401786, 2009). "Our previous studies demonstrated a central role for the Sp4 gene in hippocampal development and modulation of a variety of behaviors relevant to human psychiatric disorders." (PMID 19401786, 2009). "Increasing evidence indicates that transcription factor specificity protein 4 (SP4) may play a role in major psychiatric disorders." (PMID 25915526, 2015). "The studies on the role of Sp4 gene in hippocampal development may provide novel insights for the contribution of hippocampal abnormalities in these psychiatric disorders." (PMID 19401786, 2009). "The administration of raclopride, a dopamine D2 antagonist, significantly improved sensorimotor gating in both Sp4 heterozygous and homozygous mice but not in wildtype mice, suggesting that dopamine neurotransmission may be altered in Sp4 mutant mice as it is in human psychiatric disorders." (PMID 19401786, 2009). "On the other hand, the elucidation of Sp4 molecular pathways in the Sp4 hypomorphic mouse model will provide novel insights in our understanding of neural circuitry in the regulation of sensorimotor gating and other behaviors relevant to human psychiatric disorders." (PMID 19401786, 2009).
infection (5 papers, 2008 to 2023). The state of being infected such as from the introduction of a foreign agent such as serum, vaccine, antigenic substance or organism. "However, when we increased SP4-2 treatment to 14, 16, 20, and 24 μg/ml, R5 inhibition of infection increased proportionally to 65%, 70%, 78%, and 88%, respectively (not shown)." (PMID 18197976, 2008). "For R5-tropic infection, we observed a mean of 21% infected cells (e), which decreased to 19.9% (f), 17.5% (g), and 11.7% (h) infected cells after treatment with 1, 6, and 12 μg/ml SP4-2, respectively." (PMID 18197976, 2008). "This is in accordance with conclusions recently drawn from our previous study showing an increase in SP4 at day 1 and in both SP4 and SP8 at day 5 following CV-B4 infection." (PMID 32300341, 2020).
SP4 also shares sentences with these, for which no sentence is quoted: cardiac arrhythmias (2 papers); diabetic retinopathy (2); proliferative diabetic retinopathy (2); sarcoma (2); and autosomal recessive retinitis pigmentosa (1); astrocytomas (1); autosomal recessive cone rod dystrophy (1); AV block (1); endometriosis (1); fibrosarcoma (1); gastric cancer (1); glioblastoma (1); lung carcinoma (1); malignant glioma (1); malignant lymphomas (1); mastocytosis (1); mental retardation (1); multiple myeloma (1); Nance-Horan syndrome (1); neurodevelopmental disorder (1); oligodendroglioma (1); ovarian carcinoma (1); pneumococcal pneumonia (1); retinal disease (1); Sepsis (1); Sinus bradycardia (1).